MAP1LC3B (microtubule associated protein 1 light chain 3 beta)
Diseases named in the same sentence as MAP1LC3B in open-access papers (continued):
Sharing a sentence is not in itself a finding about the gene and the disease.
tumor (continued). "In the study, higher protein levels of MAP1LC3B and SQSTM1 were found in tumor tissues, and the high co-expression of MAP1LC3B and SQSTM1 was associated with tumorigenesis and better DFS." (PMID 34829743, 2021). "We found that protein levels of MAP1LC3B (4.41 ± 2.18 vs. 5.14 ± 1.84, p = 0.001) and SQSTM1 (0.51 ± 1.16 vs. 3.84 ± 2.24, p <0.001) were higher in the tumor tissue than in the CTAN tissues of IDC patients." (PMID 34829743, 2021). "Our results find higher protein levels of MAP1LC3B and cytoplasmic SQSTM1 in the tumor tissues of IDC patients." (PMID 34829743, 2021). "We found that protein levels of MAP1LC3B and SQSTM1 were higher in tumor tissues than in CTAN tissues in IDC patients." (PMID 34829743, 2021). "Our results show that both MAP1LC3B and cytoplasmic SQSTM1 were elevated in tumor tissues in three subsites of OSCC compared with that in adjacent normal tissues." (PMID 30477228, 2018). "In both normal and tumor tissue, the highest levels of gene expression were observed for GABARAPL2, followed by MAP1LC3B and MAP1LC3A, the lowest for MAP1LC3C." (PMID 30374741, 2018). "To the best of our knowledge, we are the first group to report that the correlation of MAP1LC3B and SQSTM1 with clinicopathological outcomes at certain subsites using the largest cohort, comprising 498 paired tumor and adjacent normal tissues of OSCC." (PMID 30477228, 2018). "The HE staining results confirmed the difference in tumor growth among the groups, while staining of CANX, MAP1LC3B, MKI67, and cleaved Caspase 3 confirmed that ND could enhance chemotherapy sensitivity in vivo by reducing the expression of CANX." (PMID 39990231, 2025). "With a tissue microarray comprised of 498 OSCC patients, including 181 BMSCC, 244 TSCC, and 73 LSCC patients, we found that the expression levels of MAP1LC3B and cytoplasmic SQSTM1 were elevated in the tumor tissues of three subsites compared with those in adjacent normal tissues." (PMID 30477228, 2018). "The SQSTM1 protein level was also found to be positively correlated with MAP1LC3B in the tumor tissues of BMSCC but not in adjacent normal tissues." (PMID 30477228, 2018). "Third, SQSTM1 was positively correlated with MAP1LC3B in the tumor tissues of BMSCC, but not in adjacent normal tissues." (PMID 30477228, 2018). "In our present study, MAP1LC3B expression was higher in tumor tissues than in adjacent normal tissues at three subsites of OSCC." (PMID 30477228, 2018). "Concurrently, autophagy-related genes such as MAP1LC3B and SQSTM1 were elevated, indicating enhanced autophagic activity that may facilitate cellular adaptation to microenvironmental stressors and contribute to tumor progression." (PMID 41394809, 2025). "Among the 25 MRGs exhibiting differential expression between the normal and tumor tissues, only MAP1LC3B, PINK1, PARK2, UBB, and UBC were significantly downregulated in the tumor tissues, while expression of the other genes was significantly upregulated in the tumor samples." (PMID 38155968, 2023). "Moreover, IHC assays revealed that m-THPC-PDT treatment obviously increased the expression of MAP1LC3B-II and decreased the expression of SQSTM1/p62 in tumor tissues, indicating that m-THPC-PDT could induce autophagy in a xenograft model." (PMID 33130826, 2020). "Interestingly, ablation of MAP1LC3B or SQSTM1 or both decreased tumorsphere formation and enhanced the killing effects of paclitaxel (PTX), implying that MAP1LC3B and SQSTM1 might modulate autophagy for tumor growth and drug resistance in BMSCC cells." (PMID 30477228, 2018). "First, the expression levels of MAP1LC3B and SQSTM1 were higher in tumor tissues than in adjacent normal tissues at three subsites—BMSCC, TSCC and LSCC." (PMID 30477228, 2018). "In this study, we compared the MAP1LC3B and SQSTM1 protein levels in tumor tissues and adjacent normal tissues in three major subsites of OSCC, including BMSCC, TSCC and LSCC." (PMID 30477228, 2018).
cancer (159 papers, 2011 to 2025). A tumor composed of atypical neoplastic, often pleomorphic cells that invade other tissues. "High expression of MAP1LC3B is associated with poor survival but also has better outcomes in patients with different types of cancer." (PMID 34829743, 2021). "Knockdown of MAP1LC3B or direct inhibition of autophagy has been shown to result in decreased cancer cell proliferation under in vitro settings." (PMID 40300005, 2025). "In both the control and cancer patients, there were positive correlations (p < 0.0001) between KRAS mutational status and the expression of MAP1LC3B, ATG5, ATG10, ATG13, and ATG14." (PMID 39057088, 2024). "In contrast, cancer patients with high MAP1LC3B expression have better outcomes, such as in early-stage non-small cell lung cancer (NSCLC)." (PMID 34829743, 2021). "Increased protein levels of MAP1LC3B and SQSTM1 are considered to be causes of autophagy inhibition or activation in various types of cancers." (PMID 34829743, 2021). "In these clusters of cancer cells, monocytes, and neutrophils, MAP1LC3B was also expressed, which is transcriptionally activated in the process of autophagy." (PMID 33204717, 2020). "Both proteins are essential for the autophagy machinery, and high expression levels of MAP1LC3B and SQSTM1 are significantly associated with an unfavorable clinicopathological outcome in several cancer types, including OSCC." (PMID 30477228, 2018). "Our results in this study demonstrate that sXBP1 binds to the promoter of Map1lc3b, which could be a potential mechanism to induce autophagy in skeletal muscle during cancer cachexia." (PMID 40655023, 2025). "High MAP1LC3B levels could result from cancer progression and reflect the low sensitivity of anti-cancer therapy." (PMID 36980957, 2023). "While mutations of autophagy genes (ATGs) are notably rare in cancer, haploinsufficiency network analyses across many cancers have shown that the autophagy pathway is frequently hit by somatic copy number losses of ATGs such as MAP1LC3B/ATG8F (LC3), BECN1/ATG6 (Beclin-1), and ATG10." (PMID 35681458, 2022). "We reconfirmed the correlational analysis data with the expression of MAP1LC3B, ATG5, ATG13, and ATG14 in cancer patients, in KRAS-mut compared to KRAS-WT (p < 0.05)." (PMID 39057088, 2024). "Expressions of MAP1LC3B and SQSTM1 have been widely used to evaluate autophagy status in mammalian cells and their clinical significance in cancer patients." (PMID 34829743, 2021). "The accumulation of MAP1LC3B and SQSTM1 plays a different role in clinicopathological outcomes and prognosis in various types of cancer." (PMID 34829743, 2021). "The other orthologous would compensate their function while silencing MAP1LC3B or/and SQSTM1 in cancer cells." (PMID 34829743, 2021). "Several target genes of miR-204, including HOXA10, MEIS1, FOXC1, MAP1LC3B, BCL2, NTRK2, SOX4 and EphB2, have been identified in different cancers." (PMID 26710269, 2015). "In addition, RTA dh404 promoted or repressed genes related to autophagy in cancer cells, including four genes (SQSTM1(p62), MAP1LC3B(LC3B), ATG5, and ATG12) in GBM8401 cells and two genes (SQSTM1 (p62) and MAP1LC3B (LC3B)) in U87MG cells." (PMID 36835414, 2023). "However, the puncta of both MAP1LC3B-II and SQSTM1 were very rare in all tissues of our TMA, likely due to the different cancer types or tissues that we used." (PMID 30477228, 2018). "Our results suggested that MAP1LC3B and SQSTM1 may modulate autophagy for cancer development, malignancy and relapse in a subsite-dependent manner." (PMID 30477228, 2018). "Therefore, the knockdown of MAP1LC3B or/and SQSTM1 might result in a defective autophagy, thus protecting cancer cells." (PMID 34829743, 2021). "Indeed, among these targets, transcription of MAP1LC3B and ATG14 genes are directly controlled by this CARM1/TFEB during starvation, a process that could be also involved in cancers when cancer cells are frequently deprived." (PMID 31861179, 2019).
infection (118 papers, 2011 to 2026). The state of being infected such as from the introduction of a foreign agent such as serum, vaccine, antigenic substance or organism. "We then showed that, following the early increase in autophagy associated with the infection by Salmonella (2h p.i.), SopE contributes to the dampening of MAP1LC3B gene expression, and of the autophagy flux in the HT-29 cell line." (PMID 36061866, 2022). "Using mice deficient in the autophagy-associated protein, Map1-LC3b (LC3b−/−), they observed increased Th17 cells in lungs upon infection." (PMID 26441964, 2015). "Similarly, mice deficient in the autophagy protein LC3B (MAP1-LC3B) exhibit increased IL-17-induced lung pathology upon infection with respiratory syncytial virus (RSV) and Map1lc3b−/− CD11b+ DC infected with RSV induce IL-17 secretion from CD4+ T cells in an IL-1-dependent manner." (PMID 30619278, 2018). "First, we confirmed that MV-Edm triggered mitophagy in NSCLCs, as colocalization of lipidated MAP1LC3B with mitochondria was massively increased following MV-Edm infection." (PMID 25004098, 2014). "At the same time, mRNA levels of Map1lc3b and Sqstm1 remained overall unchanged throughout the course of infection suggesting that increased P62 and LC3B-II levels were not caused by transcriptional upregulation, but rather accumulated by a SARS-CoV-2-induced blockage of autophagy." (PMID 34155207, 2021). "To determine whether MV-Edm infection enhances autophagic flux, we analyzed both lipidation of MAP1LC3B in presence of chloroquine and expression of SQSTM1." (PMID 25004098, 2014). "In human IAPA and CAPA patients, genes MAP1LC3B and SQSTM1, related to LAP were decreased, while CDC20, the gene encoding for the CDC20 protein which is involved in LC3 degradation, was upregulated in the superinfection group comparing to viral single infection." (PMID 36377895, 2022). "Furthermore, under Hp-WT or Hp-ΔcagA infection, the levels of MAP1LC3B-II in AGS cells transfected with the CagA expression plasmid (GFP-CagA) were decreased in comparison to that in transfected-control cells, suggesting that over-expression of CagA lead to further reduction of autophagic flux." (PMID 28983474, 2017). "Our study showed that the expression of autophagy-related genes ULK1, ATG13, ATG101, Beclin-1, ATG14, MAP1LC3A, and MAP1LC3B was significantly increased and that SQSTM1 was decreased in the muscle with pathogen infection." (PMID 33574492, 2021). "Several genes including MAP1LC3B, SQSTM1 and PLEKHM1 demonstrated a pattern wherein expression level was significantly downregulated upon SARS-CoV-2 infection (vs. no infection) in DMSO-treated ALOs and significantly upregulated in response to RMC-113 treatment." (PMID 38659941, 2024). "Furthermore, inhibition of autophagy by Baf-A1 challenge resulted in further accumulation of both MAP1LC3B-II and SQSTM1 in AGS cells after 6 h of Hp-WT or Hp-ΔcagA infection, suggesting that H. pylori CagA did not inhibit the fusion of autophagosomes with lysosomes." (PMID 28983474, 2017).
bacterial infection (4 papers, 2018 to 2025). "After 2 h of bacterial infection, 79 genes were upregulated, including MAP1LC3B encoding LC3B, the most studied gene in autophagy." (PMID 29600279, 2018).
myopathies (4 papers, 2016 to 2025). "Seven adult patients affected by COL6 myopathies underwent a controlled low-protein diet for 12 mo and we evaluated the presence of autophagosomes and the mRNA and protein levels for BECN1/Beclin 1 and MAP1LC3B/LC3B in muscle biopsies and blood leukocytes." (PMID 27656840, 2016).
MAP1LC3B also shares sentences with these, for which no sentence is quoted: glioma (18 papers); hepatocellular carcinoma (18); diabetes (15); osteosarcoma (14); pancreatic cancer (14); cervical carcinoma (10); ischemia (10); Obesity (9); lymphoma (8); colitis (7); esophageal adenocarcinoma (7); lung adenocarcinoma (7); Stroke (7); adenocarcinoma (6); Cerebral ischemia (6); lymph node metastasis (6); myeloma (6); non-small cell lung carcinoma (6); pulmonary hypertension (6); oral cancer (5); acute kidney injury (4); astrocytomas (4); esophageal cancer (4); Hyperglycemia (4); leukemia (4); liver fibrosis (4); neurodegenerative disease (4); renal cell carcinoma (4); renal clear cell carcinoma (4); adenomyosis (3).
A further 193 diseases each share a sentence with MAP1LC3B in 3 papers or fewer.